C21orf140 (chromosome 21 open reading frame 140)
Synonyms: FAM243A
Tractability: No criterion of Open Targets' tractability assessment is met for any kind of drug.
Gene: Protein-coding gene on chromosome 21 (34,400,112 to 34,401,072, reverse strand). Ensembl gene ENSG00000222018.
Homologues: Orthologues: chimpanzee C21orf140 (99% identical), macaque C21orf140 (96% identical), pig C21orf140 (80% identical), dog C21orf140 (79% identical), rabbit C21orf140 (76% identical), mouse Fam243 (71% identical), rat C11h21orf140 (69% identical).